CD86 (CD86 molecule)
Diseases named in the same sentence as CD86 in open-access papers (continued):
Sharing a sentence is not in itself a finding about the gene and the disease.
tumor (continued). "Antitumor effects and prolonged survival correlated with strong antigen-specific T-cell responses by analyzing CD11c+CD86+ DC, CD11b+F4/80+ MΦ cells, increased ratio of Teff/Treg in the tumor microenvironment, and higher secretion levels of Th1 proinflammatory cytokines in serum." (PMID 29263903, 2016). "Additionally, the percentage of CD11b+ GAMs expressing high levels of CD86 and the ratio of GAMs expressing high levels of CD86 relative to those expressing high levels of CD206 were significantly higher in whole tumor extract of Nrp1MgKO mice." (PMID 26755653, 2016). "Furthermore, the expressions of CD80 and CD86 in Treatment group were significantly higher than Tumor group especially on the back of a few time points the same as the results of CD11c." (PMID 27669687, 2016). "The other protein type includes proteins that exist in specific types of exosomes; for example, MHC and costimulatory CD80 or CD86 molecules are abundant in exosomes surface originating from DCs and B lymphocytes, and a number of tumor antigens are contained in tumor cell-derived exosomes." (PMID 27686593, 2016). "We have previously shown that the invasion of ID8DV tumor associated immune suppressed CD11c+ antigen presenting cells by uracil auxotrophs triggered the expression of the T-cell receptor costimulatory molecules CD80 and CD86." (PMID 27447180, 2016). "We demonstrate that induction of apoptosis in lung tumors treated with low doses of CO is associated with increased CD86 expression and activation of mitogen-activated protein kinase (MAPK)/extracellular signal-regulated kinases (Erk) 1/2 pathway in tumor microenvironment." (PMID 26993595, 2016). "Immunofluorescence analysis of the frozen tumor sections from CTX-ACT-treated mice revealed that certain YFP-labeled DCs displayed an mature phenotype characterized by the expression of MHC-II and CD86, indicating that some mature DCs were present in the tumor areas." (PMID 27855783, 2016). "Interestingly, low dose of CO at 100 ppm was effective in suppressing tumor xenograft growth and increasing expression of CD86 on infiltrating/residential macrophages." (PMID 26993595, 2016). "Importantly, RdB/IL12/shVEGF-treated tumor tissues exhibited markedly higher co-localization of CD86+/CD11c+ DCs than the other treatment groups." (PMID 27821803, 2016). "To evaluate whether CO modulates polarization of myeloid cells in tumor stroma in this model, we measured the number of CD86/CD197-postive M1-like myeloid cells by flow cytometry." (PMID 26993595, 2016). "In a preclinical model, an M-CSF blockade with the small inhibitor molecule BLZ945 decreased immunosuppressive macrophage (CD14/CD206) activation and increased inflammatory macrophage (HLA-DR/CD86) activation as well as DC and T cell infiltration, resulting in inhibition of tumor progression." (PMID 28536380, 2016). "Interestingly, CO at 100 ppm induced expression of M1 macrophage marker CD86, indicating skewing of this specific population in the tumor microenvironment." (PMID 26993595, 2016). "Furthermore, immunofluorescence staining of tumor tissues with CD11c-, CD86-, and NK-1.1-specific Abs revealed that RdB/IL12/shVEGF induced the greatest infiltration of immune cells (DC and NK) into the tumor tissues." (PMID 27821803, 2016). "One may envisage that such a decrease in intracellular CTLA-4 levels would decrease the T-cell activation threshold during contact with dendritic cells that express CD80 and CD86 and enhance their proliferation and anti-tumor abilities." (PMID 26110267, 2015). "Furthermore, TIDC expressed higher level of MHC Class II and of costimulatory molecules CD86 than CD11c+ spDC from naïve tumor-free mice." (PMID 26491691, 2015). "The rationale was to costimulate tumor-reactive T cells with CD86 before IL-2 exposure." (PMID 26343191, 2015).
tumor (continued). "M1, the classically activated MΦ/Mo induced by IFN-γ and bacterial products, display high antigen presentation efficiency due to upregulation of MHCII (HLA-DR) and co-stimulatory molecules (CD80 and CD86), express high levels of IL-12 and low IL-10, and thus activate Tc1/Th1 anti-tumor responses." (PMID 26579227, 2015). "Phagocyte activation not only promotes tumor-associated antigen presentation and upregulates costimulatory B7 family molecules such as CD80/CD86 to trigger anti-tumor lymphocyte activation, but also initiates counter-regulatory signals that attenuate activation." (PMID 25871398, 2015). "We found that HIFU treatment decreased circulating B16F10 cells and pulmonary metastasis nodules while increased IFN-γ and TNF-α in the peripheral blood and cumulative mouse survival, which was associated with inhibition of miR-134 expression and activation of CD86 expression in tumor tissues." (PMID 26485753, 2015). "An increased number of CD86+ macrophages were present in the GPC3-expressing tumor." (PMID 24992906, 2014). "Tumor stroma contained a lower number of CD86(+) cells than lamina propria of the normal tissue." (PMID 24901518, 2014). "We further speculate that the increased presence and activation of CD86+ antigen presenting cells may also increase tumor specific CD4+ T cell activation with all the downstream effects such as increased B cell help and anti-tumor antibody production." (PMID 26824927, 2013). "This hypothesis was tested by inducing the expression of CD80/CD86 molecules on tumor cells prior to injection into mice." (PMID 23450201, 2013). "Forced expression of CD80/CD86 in tumor cells resulted into CD8+ T cell-dependent tumor rejection." (PMID 23450201, 2013). "In addition, CD80 and CD86 surface expression was used to gauge the activation profile of CD11c+ DC found within the tumours." (PMID 24251770, 2013). "Our data showed that ligation of CD86 with CTLA4Ig in vitro could significantly enhance the tumor-killing ability of NK-92MI cells to K562 tumor cells, which suggested that CD86 on NK cells might be involved in the process of regulating NK cell function." (PMID 24349559, 2013). "Hence we assayed infiltration of CD86+ cells in tumor tissue as a proxy marker of potential anti-tumor CD8+ T cell responses." (PMID 26824927, 2013). "Other factors which may influence the rate of cell killing are firstly susceptibility of individual tumor cell lines to lysis and secondly the presence of cofactors such as CD80 and CD86 on the tumor cells which may augment killing." (PMID 23263452, 2013). "Furthermore, TLR9 agonist activated NKDCs by upregualting the expression of both CD80 and CD86, while RT increased the tumor infiltration of NKDCs." (PMID 22666458, 2012). "Furthermore, tissue immunofluorescence staining evidenced a marked elevation in the expression of the M1 macrophage marker CD86 in tumor tissues treated with GEM + RP-6306@BxPC-3M, corroborating the robust antitumor efficacy of GEM + RP-6306@BxPC-3M in the CDX model with minimal systemic toxicity." (PMID 40664640, 2025). "However, high expression of ALG3 may suppress the function of CD68+CD86+ macrophages or reduce their recruitment in the tumor microenvironment, thereby weakening the anti-tumor immune response." (PMID 40475760, 2025). "Therefore, we hypothesized that C4 CD86+ Memory B cells might be able to promote tumor progression through the CD46-JAG1 pathway." (PMID 39744570, 2025). "Finally, analysis of CNV patterns in key co‐stimulatory and co‐inhibitory genes (e.g., CD80, CD86, PD‐L1) revealed a distinct inverse relationship between Q1 and Q4 groups: Q1 tumours exhibited higher frequencies of gene amplifications, whereas Q4 tumours demonstrated more frequent deletions." (PMID 40596639, 2025).
tumor (continued). "Moreover, the expression levels of CD86 (M1 macrophage marker) and CSF1R (M2 macrophage marker) were positively correlated with those of BECN1 (autophagy regulator) and BCL2 (only CD86) that were in turn correlated with MTOR expression in tumor B cells and in the CD86+ macrophage subtype." (PMID 41415285, 2025). "Moreover, the IHC results showed that the expression levels of Ki‐67, vimentin and CD206 were significantly lower and that the expression levels of E‐cadherin and CD86 were significantly greater in the tumor tissues of the sh‐MFGE8 migrasome group than in those of the sh‐NC migrasome group." (PMID 40056029, 2025). "Similarly, when bone marrow-derived macrophages from CD45.1 mice were transferred into CD45.2 tumor-bearing mice, D166 treatment increased the expression of M1 macrophage markers (CD86 and iNOS) in CD45.1 macrophages, whereas the expression of M2 markers decreased." (PMID 40520004, 2025). "In addition, DCs (CD45+CD11c+MHC-II+) and tumor-associated macrophage (TAMs), regardless of M1-like macrophage (CD11b+F4/80+CD86+) or M2-like macrophage (CD11b+F4/80+CD206+) were also less infiltrated in KL tumors than KP tumors." (PMID 38291516, 2024). "However, the tumor treated with combination therapy maintained CD80/CD86–CTLA-4 signaling." (PMID 39298276, 2024). "Therefore, the decline of CD80 positive cells in the present study may point to the activation of T-cell mediated anti-tumor immune response and a difference between the function of CD86 and CD80 in CCH seems likely." (PMID 38962703, 2024). "Hence, we obtained tumor-infiltrating DCs and analyzed the percentage of total DCs and their three subsets cDCs1, cDCs2, and InfDCs, as well as CD86 expression among subsets." (PMID 38812523, 2024). "Furthermore, we proved the functional importance of co-stimulatory molecules by showing that co-treatment of hRT/lena-treated mice with antibodies blocking CD70, CD83, and CD86 worsened primary and, more prominently, secondary (abscopal) tumor control and diminished overall survival of the mice." (PMID 38646638, 2024). "In particular, CD80 with its later increase seems to be a useful indicator of CCH tumor cell maturation in this scenario, whereas the consistently high expression of CD86 may be interpreted as an indicator of an onset of tumor cell maturation earlier than the clinically apparent stage 1." (PMID 39619201, 2024). "In addition, CD80 and CD86 are also involved in anti-tumor immunity." (PMID 37614091, 2024). "Interestingly, we found that TAM Macro‐2 was preferentially enriched in the interstitial region but also infiltrated the tumor region, indicating that tumor cells may hijack CD68+CD86− to restrain the immune response and promote tumor growth." (PMID 38483933, 2024). "Interestingly, we found that introducing Let-7i to tumours resulted in enhanced CD86 expressions in APCs in the draining LNs, an important costimulatory molecule that activates and differentiates T cells through interaction with CD28 and is associated with improved APC function." (PMID 38554167, 2024). "Interestingly, the population of monocytic (Mo)-MDSCs was clearly downregulated, along with the increased expression of MHCII and CD86 at the same time as compared to those in tumor-bearing control, indicating that cryo-thermal therapy promoted Mo-MDSCs maturation." (PMID 38827732, 2024). "The upregulation of CD1C, CD40, CD80, and CD86 on Bregs shown in our study indicated that Bregs might exhibit a strong ability of antigen presentation in the MPE immune microenvironment in vivo due to tumor antigen stimulation." (PMID 37432957, 2023). "The mRNA expression levels of genes characteristics of a tumor-supportive macrophage phenotype, including Arg-1, were also downregulated by shMYBL2-CM, while those of the cytotoxic response-related genes IL-1β, IL-12 A, and CD86 were increased by supernatants of shMYBL2 cells." (PMID 37865750, 2023).
tumor (continued). "It followed that CD86 might be significantly involved in the tumor immune microenvironment in HGG." (PMID 38154107, 2023). "Prognostic analysis of the expression of CD86 in cancer tissues showed that CD86 could inhibit tumor progression and prolong the overall survival time of patients for 3 years (P = 0.04), which further verified the effect of M1 macrophages in inhibiting tumor growth." (PMID 37306737, 2023). "In addition, some tumors prompt regulatory T cells (Tregs) to express CTLA-4, leading to downregulation of CD80/CD86 expression in antigen-presenting cells, resulting in reduced production of cytokines such as interleukin 2, which affects the body’s anti-tumor capacity." (PMID 37622124, 2023). "The flow cytometric results showed that the HRMTF NPs could remarkably increase the proportion of the mature DCs (CD11c+CD80+CD86+) both in the primary tumor (39.01%) and in the distant tumor (41.77%) relative to that in the control group (primary tumor: 15.76%; distant tumor: 20.70%)." (PMID 36930774, 2023). "Conversely, CD80/CD86-targeted CAR-T (CTLA4-CAR), which comprises the extracellular and transmembrane portions of human CTLA4, the cytoplasmic region of human CD28, and the intracellular domains of human CD3z, was designed to destroy CD80/CD86-associated tumor cells in vitro and vivo." (PMID 37457699, 2023). "The expression of NUPR1 was highly correlated with tumor‐associated macrophage markers including C‐C motif chemokine ligand 2 (CCL2, R = 0.392, p < 0.001), C‐C chemokine receptor type 5 (CCR5, R = 0.323, p < 0.001), CD80 (R = 0.302, p < 0.001), and CD86 (R = 0.381, p < 0.001)." (PMID 36468653, 2023). "Therefore, we concluded that high infiltration of CD206+ macrophages, low infiltration of CD86+ macrophages, and a high ratio of CD206+/(CD86++CD206+) macrophages would be markedly associated with advanced stage and a high rate of tumor recurrence and mortality." (PMID 37342343, 2023). "Although neither treatment had effect on the total number of tumor associated macrophages, X-body treatment shifted the bias of macrophage to a more M1 -like pro-inflammatory phenotype as indicated by the expression of iNOS and CD86." (PMID 36451853, 2022). "It is possible that the CD86/CD28 costimulatory signal primarily affected the survival and activation of memory CD4 T-cells, which were associated with OS and RFS and could kill tumor cells." (PMID 35463956, 2022). "MC-C tumor immunogenicity was associated with the capacity of MC-C tumor lysate to promote the maturation of DC as evaluated by the up-regulation of cell surface receptors CD80, CD86 and MHC II as well as production of the inflammatory cytokines TNF-α and IL-12p70." (PMID 35922755, 2022). "Classically activated macrophages (M1) are involved in Th1 responses, responsible for phagocytosing invading microorganisms and tumor cells, with the capacity to produce large amounts of pro-inflammatory cytokines, which may justify the expression of CD86 in both evaluated tumor sizes." (PMID 36559209, 2022). "In addition to CD86 protein expression and co‐expression of CD68 and CD163 status, statistically remarkable clinicopathological features that were associated with RFS were TNM stage (P =.001) and tumour differentiation (P =.010)." (PMID 34964155, 2022). "Therefore, in future clinical studies, considering neoadjuvant therapy modalities and CTLA-4/CD86 expression during ICIs, combination therapy might effectively block more immune-evasive tumor mechanisms." (PMID 36428666, 2022). "Among the 6 immune checkpoints, CTLA4, CD86, and PDCD1LG2 were highly expressed in the high-risk group (Wilcoxon rank-sum test, p < 0.05), suggesting that these genes may serve as key targets for anti-tumor therapy in CRC." (PMID 35719389, 2022).
tumor (continued). "M2 macrophages expressing CD86− CD206+ in the Me49-DC-Exo group were significantly reduced compared with tumor-bearing mice treated with PBS (p < 0.05), suggesting that exosomes from T. gondii-infected DC could significantly inhibit macrophage polarization to M2 phenotype." (PMID 35600340, 2022). "ATRA treatment alone downregulated the expression levels of CD86 and F4/80 and slightly increased the level of CD11c on MDSCs compared to those in the tumor-bearing control group, which indicated that ATRA treatment alone could not regulate the phenotypic maturation of MDSCs." (PMID 36389684, 2022). "Notably, MHCII and CD86 expression was significantly decreased in WT BMDMs after 48 h, while there was no obvious change in Fats−/− BMDMs, suggesting that FATS deficiency increases M1 polarization under tumor conditions." (PMID 34262035, 2021). "To determine whether CTLA4-chimera-transduced T cells (CTLA4-T) could specifically recognize and kill CD80-positive or CD86-positive tumor cells, we performed cytotoxicity assays by co-culturing CTLA4-T cells or genetically modified control T cells (GFP-T) with the tumor cells." (PMID 33868277, 2021). "Importantly, expression of CD80 and CD86 on monocultured DCs treated with the chemotherapeutic agents did not significantly differ from vehicle, indicating that the immunogenic effects of chemotherapy rely on their interaction with tumor cells." (PMID 32560232, 2020). "Thus, increased CD86 expression in Stat3∆/∆ CD103+ cDC1s in the TME post vaccination may contribute to the increase in tumor antigen-specific CD8+ T cells." (PMID 31947933, 2020). "However, considering the expression of CD80 and CD86 on APCs, using these receptors might induce an untimely immune reaction against the HAdV, preventing infection of tumor cells in the TME." (PMID 32957644, 2020). "Furthermore, the expression levels of co-stimulatory molecules, including CD80, CD86, and I-ab, were higher on tumor-infiltrating DCs from lent-miR-138-5p treated mice compared with other groups, indicating enhanced maturity of tumor-infiltrating DCs from lent-miR-138-5p treated A549 bearing mice." (PMID 32754587, 2020). "Besides, CD80 and CD86 in the body can enhance the immune response of cells in vivo to tumor cells." (PMID 31223571, 2019). "CD80 and CD86 are also widely expressed in the hematological tumor microenvironment, and studies have shown that deletion of these genes may lead to failure of anti-tumor treatments." (PMID 31195368, 2019). "In addition, CD86, an activation receptor found on several immune cell types, including B cells, NK cells, and monocytes/macrophages, was also more highly expressed by tumor-infiltrating cells in PRL3-zumab-treated tumor sections." (PMID 31171773, 2019). "This study highlights how the loss of mature miRNAs in TAMs during tumor progression leads to increased classically activated TAMs, improved CD8 response, and decreased CD8 suppression, which was associated with higher expression of CXCL10, CD86, and CXCL9 in the tumors." (PMID 31710308, 2019). "Moreover, co-electroporation of CD86 and 4-1BBL could further change the phenotype and enhance the in vivo anti-tumor activity." (PMID 28523432, 2017). "Additionally, mice fed the KD had reduced expression of CD86 and PD-L1 on the tumor cells." (PMID 27178315, 2016). "Similarly, autologous whole tumor cells could be transduced with the CD86 (B-7) molecule to increase the priming of anti-tumor T cell responses." (PMID 26343191, 2015). "Thus, HIFU-induced expression of CD86 may be at least in part contribute to HIFU-enhanced anti-tumor immunity." (PMID 26485753, 2015). "Indeed, we did observe the transfer of HLA-DR and CD86 molecules from DC-Exo to tumor cells." (PMID 25646096, 2014). "Importantly, this also suggests that measuring the expression of Fas, CD80 and CD86 in patient tumor samples may be used as a biomarker for patient that might benefit from this treatment." (PMID 25227919, 2014).